RN7SKP130 (RN7SK pseudogene 130)
Gene: Miscellaneous RNA gene on chromosome 7 (2,999,094 to 2,999,394, forward strand). Ensembl gene ENSG00000201794.
Homologues: Orthologues: chimpanzee 7SK (98% identical). Paralogues in human: 7SK (77% identical), RN7SKP78 (75% identical), RN7SKP79 (75% identical), RN7SKP90 (75% identical), RN7SKP176 (75% identical), RN7SKP180 (75% identical), RN7SKP72 (75% identical), RN7SKP9 (75% identical), RN7SKP133 (74% identical), RN7SKP124 (74% identical), RN7SKP240 (74% identical), RN7SKP255 (74% identical), and 283 more.